PCDH8 (protocadherin 8)
Diseases named in the same sentence as PCDH8 in open-access papers (continued):
Sharing a sentence is not in itself a finding about the gene and the disease.
tumor (continued). "Thus, the PCDH8 gene affects immune cells and related molecules in the tumor microenvironment, and its overexpression is correlated with poorer prognosis in THCA." (PMID 38368303, 2024). "These pathways align with the role of PCDH8 in the tumor microenvironment and immune response." (PMID 38368303, 2024). "Thus, PCDH8 promotes tumor cell proliferation and viability in THCA, potentially being an important driver of THCA progression." (PMID 38368303, 2024). "Methylation could occur in PCDH8, PCDH10, and PCDH17 in both PC tumor tissue and serum, and is associated with poor prognosis and shorter biochemical relapse-free survival." (PMID 33369468, 2020). "In addition, PCDH8 methylation significantly correlated with advanced stage, high grade, larger tumor size, tumor recurrence and progression in NMIBC." (PMID 25927589, 2014). "The exact function of PCDH8 protein is unknown, but there is increasing evidence for the importance of this family of proteins as potential tumor suppressors possibly via disruption of cell-cell communication necessary for tissue organization." (PMID 24454902, 2014). "Genes linked to adhesion and structural regulation (Myopodin, PRAC, and PCDH8) were also significantly associated with reduced PFS and RFS, indicating that epigenetic disruption of cell–cell adhesion and cytoskeletal architecture contributes to early tumor dissemination." (PMID 41377897, 2025). "Similarly, PCDH8 can also drive or inhibit tumor cell phenotypes in a context-dependent manner." (PMID 39796709, 2024). "We found that PCDH8, which acts as a tumor-suppressor gene in multiple types of cancer and inhibits tumor cell proliferation, invasion and migration, was downregulated in clusters 3 and 4, suggesting that tumor cells may be more aggressive in the two clusters with lower PDCH8 expression." (PMID 34567094, 2021). "For instance, PCDH8 and PCDH20 are considered tumour suppressors, while PCDH11Y functions as an oncoprotein." (PMID 35864095, 2022). "The role of PCDHs in this group of neoplasms has been evaluated in fifteen studies, and the most re-searched are PCDH7, PCDH8, PCDH9, and PCH10." (PMID 33369468, 2020). "Comparable results were obtained for PCDH8 and PCDH10, whose methylation correlated with higher tumor stages, baseline PSA level, lymph node metastasis, and recurrence (p < 0.05), also acting as independent prognostic biomarkers in serum-based cohorts (p < 0.001–0.05)." (PMID 41008642, 2025). "Only the methylation changes in PCDH8 and TFAP2B were related to the amount of tumor mass or the dynamics of tumor growth, thus may potentially supplement imaging data on SRMs’ growth." (PMID 36555747, 2022). "PCDH8 and PCDH17, in contrast, may have multiple tumor suppression functions, such as involvement in cell-cell adhesion, signal transduction, and growth control, although the exact function of both the PCDHs is poorly understood." (PMID 33369468, 2020). "Little is known about the functions of PCDHs, but some members, such as PCDH8 and PCDH10, have been shown to suppress tumor activity, suggesting that PCDHs may act as tumor suppressors by influencing tumor growth and metastasis." (PMID 31526370, 2019). "Notably, tumor-suppressive roles have been reported for CAMK2B, EGR3, NPAS2, PCDH8, and RGS6." (PMID 39796709, 2024). "PCDH8 methylation was detected in tumor tissues and not in non-tumor tissues." (PMID 33369468, 2020). "In addition, according to a study, PCDHs located on chromosome 13q21, such as PCDH8, PCDH9, PCDH17, and PCDH20, may be involved in tumor suppression." (PMID 33369468, 2020). "Although the 5-aza-2′-deoxycytidine treatment was non-specific, thus the activation of other hypermethylated tumor suppressors could be producing the effect, the re-introduction of PCDH8 demonstrates the specific importance of this gene." (PMID 24454902, 2014).
tumor (continued). "PCDH8 hypermethylation correlated with poorer patient survival in one cohort where it represented a more significant prognostic marker for patient survival than tumor stage, grade or dimension, but was not statically significant in the second cohort, although a trend was present." (PMID 24454902, 2014).
cancer (11 papers, 2014 to 2024). A tumor composed of atypical neoplastic, often pleomorphic cells that invade other tissues. "PCDH8 was significantly elevated in cancer tissues and associated with poor prognosis, several clinical factors, and immune cell and checkpoint abundance." (PMID 38368303, 2024). "While some studies have provided indirect evidence that PCDH8 has cancer-promoting properties, this association is controversial." (PMID 38368303, 2024). "The loss of PCDH8 is known to promote oncogenesis in epithelial human cancers by disrupting cell-cell communication dedicated to tissue organization and repression of mitogenic signaling." (PMID 27029003, 2016). "Using data from the Cancer Drug Sensitivity Genomics database, we investigated the relationship between PCDH8 expression and the IC50 values of various drugs." (PMID 38368303, 2024). "These pathways indicate the potential involvement of PCDH8 in cell cycle regulation, immune signaling, and cancer-related pathways." (PMID 38368303, 2024). "PCDH8 is located within a cluster of protocadherins conserved between humans and mice and inhibits the proliferation and migration of cancer cells by expanding epithelial cells." (PMID 32226505, 2020). "The frequency of PCDH8 and PCDH17 methylation is high in this cancer, and the PCDHs are associated with malignancy clinicopathological characteristics and unfavorable prognosis." (PMID 33369468, 2020). "It was previously shown that expression levels of protocadherins, such as PCDH8, PCDH10, and PCDH20, were downregulated by promoter methylation in various carcinomas, which were strongly associated with advanced cancer or poor outcome." (PMID 27351130, 2016). "In our study, we initially assessed the expression of PCDH8 across 32 types of human cancer." (PMID 38368303, 2024). "PCDH8 expression varied among these cancer types compared to their corresponding normal tissues." (PMID 38368303, 2024). "These pathways included the canonical Wnt signaling pathway, mitotic nuclear division, regulation of RNA stability, G2/M transition of mitotic cell cycle, and regulation of mRNA catabolic process, providing insights into downstream regulatory mechanisms of PCDH8 in cancer progression." (PMID 38368303, 2024). "Some reports showed that PCDHs are dysregulated in various cancers, such as PCDH10, PCDH17 and PCDH8." (PMID 39123216, 2024). "The absence of protocadherin (PCDH) proteins, such as PCDH8, impacts the development of various types of human cancers, including colon, liver, renal, prostate, breast, nasopharyngeal, and lung cancer, as well as astrocytoma." (PMID 38368303, 2024). "Also, HOPX was correlated with genes in a manner toward suppression of cancer cell progression; downregulation of TNRC6C, PAX8, TSHR, DYRK1A/B, and SLIT3 (pro-proliferation/migration), and upregulation of PCDH8/9, CDC42EP3/4/5, and TJP3 (anti-proliferation/migration)." (PMID 31666923, 2019).
infection (8 papers, 2016 to 2025). The state of being infected such as from the introduction of a foreign agent such as serum, vaccine, antigenic substance or organism. "In addition to the non-clustered PCDH8 and PCDH9 genes, several clustered PCDH genes were upregulated after 16 h of infection." (PMID 28993767, 2017).
PCDH8 also shares sentences with these, for which no sentence is quoted: pyelonephritis (20 papers); urinary tract infection (13); colibacillosis (7); septicemia (5); bacteremia (2); cystitis (2); diarrhoea (2); mantle cell lymphoma (2); nasopharyngeal carcinoma (2); pyometra (2); adenoma (1); bladder urothelial carcinoma (1); brain tumors (1); breast invasive carcinoma (1); cellulitis (1); cholangiocarcinoma (1); chronic sinusitis (1); coeliac disease (1); colon adenocarcinoma (1); colorectal cancer (1); depression (1); endocervical adenocarcinoma (1); epilepsy (1); esophageal carcinoma (1); lung carcinoma (1); lung squamous cell carcinoma (1); mastitis (1); microphthalmia (1); Neurodevelopmental delay (1); Neurological Disease (1).
A further 12 diseases each share a sentence with PCDH8 in 1 paper.